IFNG (interferon gamma)
Diseases named in the same sentence as IFNG in open-access papers (continued):
Sharing a sentence is not in itself a finding about the gene and the disease.
Anxiety (77 papers, 2012 to 2026). Intense feelings of nervousness, tension, or panic often arise in response to interpersonal stresses. "Increased anxiety in injured mice that received a high-salt diet was associated with microgliosis and a proinflammatory microglial transcriptomic signature, including upregulation in interferon-gamma, interferon-beta and oxidative stress–related pathways." (PMID 39045090, 2024). "These pro-inflammatory cytokines (such as IFNγ or TNFα) then reach the brain via the humoral, neural and cellular routes, where they cause the already mentioned shift in balance from M2 to M1 activation in microglia (or macrophages), thus, causing anxiety." (PMID 33970950, 2021). "It was hypothesized that both AVP and OXT would have preventative effects on social stress-induced deficits in social behavior and increased anxiety and that these effects would be associated with changes in TNFα and/or IFNγ in juvenile F2 females." (PMID 28018290, 2016). "It was hypothesized that maternal AVP and OXT treatment would have preventative effects on social stress-induced deficits in offspring anxiety and social behavior and that these effects would be associated with changes in interferon-γ (IFNγ)." (PMID 28018290, 2016). "Due to the link between anxiety and inflammation, expression of IL-1β, TNFα, and IFNγ genes was measured in the ileum and colon." (PMID 37960288, 2023). "With regard to their behavior, IFNG−/− mice display decreased anxiety- and depressive-like behaviors as well as heightened emotionality in several paradigms." (PMID 30306457, 2019). "CSS F2 female juvenile offspring had elevated IFNγ levels and exhibited increased repetitive/perseverative and anxiety behaviors and deficits in social behavior." (PMID 28018290, 2016). "Control and CSS-exposed F1 dams were administered IN saline, AVP, or OXT during lactation and the F2 juvenile female offspring were assessed for basal plasma IFNγ and perseverative, anxiety, and social behavior." (PMID 28018290, 2016). "Individuals showing stress-induced decreases in CC16 in the serum display higher stress-induced anxiety and distress, and an increased production of IFNγ during the stress condition." (PMID 24228900, 2013). "Taken together, these analyses indicated that colonic iNOS may be protective against extra-colonic inflammation, and that IFNγ in the MLNs may coordinate the gut-brain inflammatory responses that influence anxiety-like behavior as well as systemic IL-17A." (PMID 35216112, 2022). "While this could be a direct relationship to anxiety, IFNγ was also related to serum TNFα and IL-17A, the latter of which was also significantly associated with both hippocampal IL-17A and to anxiety-like behavior." (PMID 35216112, 2022). "Interestingly, the levels of IFNγ in this brain section are strongly related to anxiety and unconditioned fear and TGFβ and iNOS with the damage in the long-term memory." (PMID 33322180, 2020). "Taken together, these results support the hypothesis that maternal AVP and OXT treatment have context- and behavior-specific effects on peripheral IFNγ levels and perseverative, anxiety, and social behaviors in female offspring of early-life social stress-exposed dams." (PMID 28018290, 2016). "Thus, the IFNγ relationship to anxiety-like behavior may also occur through other cytokines." (PMID 35216112, 2022). "However, the finding that mesenteric-lymph-node IFNγ was related to anxiety-like behavior was not expected." (PMID 35216112, 2022). "Thus, subjects with psychological stress-induced distress and anxiety showed significantly greater increases in IFNγ and lower IL-10 than those without distress and anxiety." (PMID 24228900, 2013).
visceral leishmaniasis (77 papers, 2004 to 2025). A severe form of leishmaniasis characterized by irregular bouts of fever, substantial weight loss, swelling of the spleen and liver, and anemia (which may be serious). "Among several conditions, plasma levels of IFNγ have been suggested as a clinical marker to follow disease/recovery after visceral leishmaniasis caused by Leishmania infection." (PMID 33224151, 2020). "Visceral leishmaniasis (VL) is associated with increased circulating levels of multiple pro-inflammatory cytokines and chemokines, including IL-12, IFNγ, and TNFα, and elevated expression of IFNγ mRNA in lesional tissue such as the spleen and bone marrow." (PMID 25275531, 2014). "Whereas the whole blood assay is widely used to measure antigen-specific cytokines, such as IFNγ and IL-10 in patients with visceral leishmaniasis, little is known about this assay in CL patients." (PMID 39933183, 2025). "From the results of DisGeNET, the hub genes IL10, IL6, CXCL8, CSF2, IFNG, IL1B, and TNF were causing Visceral Leishmaniasis; IL10, IL4, CXCL8, IFNG, IL1B and TNF found to cause Cutaneous Leishmaniasis and Urban Cutaneous Leishmaniasis." (PMID 36989283, 2023). "During L. donovani infection, leading to visceral leishmaniasis, depletion of IL-10 was also shown to induce increased production of IL-12 and IFNγ." (PMID 35464430, 2022). "Studies of patients with symptomatic visceral leishmaniasis infected L. donovani or L. infantum identified IFNG as upregulated in the peripheral blood when compared with healthy controls." (PMID 33793565, 2021). "Understanding the cellular source/s of IFNγ in the WB is critical to our reinterpretation of the immunologic defects in kala-azar." (PMID 25275531, 2014). "A study conducted on human patients suffering from visceral leishmaniasis due to infection with Leishmania donovani (L. donovani) showed that these patients had CD4+ T cells failing to express significant amounts of IFNγ and MIF, thereby failing to control infection." (PMID 35464430, 2022). "IL-10 is a critical regulatory cytokine involved in the pathogenesis of visceral leishmaniasis caused by Leishmania donovani and clinical and experimental data indicate that disease progression is associated with expanded numbers of CD4+ IFNγ+ T cells committed to IL-10 production." (PMID 22911108, 2012). "Thus supplementation of cholesterol together with IFNγ may be a new approach to treat drug unresponsive Kala-azar cases." (PMID 21931549, 2011). "Despite the presence of significant levels of systemic Interferon gamma (IFNγ), the host protective cytokine, Kala-azar patients display high parasite load with downregulated IFNγ signaling in Leishmania donovani (LD) infected macrophages (LD-MØs); the cause of such aberrant phenomenon is unknown." (PMID 21931549, 2011). "The kala-azar patients do not respond to the host-protective cytokine IFNγ at the active stage of the disease, the cause of which is unknown." (PMID 21931549, 2011). "In this context, pretreatment serum levels of interferon-gamma (IFN-γ), tumor necrosis factor-α (TNF-α), IL-4, IL-6, IL-8, IL-10, and IL-27 are elevated in Brazilian individuals with untreated kala-azar." (PMID 41003560, 2025). "The increased production of IFNγ by CD8+ lymphocytes that we observed after IRF5 silencing was particularly interesting, in view of another recent study relating to chronic visceral leishmaniasis in mice." (PMID 33369221, 2021). "Therapy with AmB induced elevated production of TNFα, IFNγ and IL-12 in splenocytes of treated mice, and PBMC of kala-azar patients with reduced IL-4, IL-10 and TGFβ production." (PMID 25884796, 2015). "However, the Th1/IFNγ-mediated response alone is not sufficient to protect against disease, since visceral leishmaniasis patients are able to produce IFNγ in response to Leishmania antigen." (PMID 23300451, 2013).
cutaneous leishmaniasis (75 papers, 2006 to 2025). Leishmaniasis affecting the skin. "However, since another intronic variant in IFNG has been correlated with both low levels of IFN-γ in humans and susceptibility to cutaneous leishmaniasis, more studies on the rs22078594 variant will be needed to elucidate its potential role in the regulation of the immune response." (PMID 36443886, 2022). "In cutaneous leishmaniasis, it was also shown that blocking PD-1 resulted in increased production of IFNγ by circulating T cells." (PMID 35749568, 2022). "A study showed that Leishmania amazonensis, a parasite causing cutaneous leishmaniasis, can upregulate PDL-1 on both mouse and human neutrophils, these neutrophils have the ability to suppress the production of IFNγ by CD8+ T cells." (PMID 35749568, 2022). "In line with this, mice infected with Trypanosoma brucei were shown to be resistant to cutaneous leishmaniasis through the induction of IFNγ generating a hostile pro-inflammatory environment impairing L. major colonization of the skin." (PMID 35039441, 2022). "Interferon-gamma (IFN-Υ) is the essential cytokine for inducing protective immunity against cutaneous leishmaniasis." (PMID 25371808, 2014). "IFNγ and IL-4 are the key players involved both in VL and cutaneous leishmaniasis." (PMID 27494323, 2016). "This study also showed that blockade of LIGHT with soluble receptors in mice infected with L. major, a cause of cutaneous leishmaniasis, resulted in reduced IL-12 generation, associated with diminished CD4+ T cell IFNγ production and increased parasite growth and disease." (PMID 21998581, 2011). "In murine models, IFNγ- and IL-10-producing CD4+ T cells emerge during experimental infection with Toxoplasma gondii and in non-healing cutaneous leishmaniasis, where they were shown to protect mice against immune-related pathology at the cost of pathogen persistence." (PMID 41000872, 2025).
schizophrenia (73 papers, 2012 to 2026). A major psychotic disorder characterized by abnormalities in the perception or expression of reality. "Among cytokine genes, significant association was observed with pro-inflammatory cytokine gene polymorphisms of IL1A, IL6, TNFA, and IFNG with schizophrenia in our study population." (PMID 27177030, 2016). "IFNG rs2069718 was found to be associated with schizophrenia in our population at the genotypic level with increased frequency of AA genotype in schizophrenia patients (P = 0.026)." (PMID 27177030, 2016). "Frequency of the IFNG +874T>A[T] allele was 48.88 %, while frequency of the A allele was 51.12 % in schizophrenia subjects." (PMID 24065520, 2013). "Our results do not support the association of polymorphisms in IL2, IL6 and IFNG genes with schizophrenia." (PMID 24065520, 2013). "Collectively, these results suggest that IFNγ signalling may impact neurodevelopment in a way that predisposes to schizophrenia, but that this may be independent from genetic effects." (PMID 35716830, 2022). "We previously demonstrated that acute exposure of neural progenitor cells (NPCs) and neurons derived from human induced pluripotent stem cells (iPSCs) to IFNγ results in gene expression changes in genes associated with schizophrenia and autism, and altered neuronal morphology in exposed neurons." (PMID 36186864, 2022). "Despite these findings, it is unclear whether and how elevated levels of IFNγ impact the development of neurons, and if this could contribute to increased risk for schizophrenia." (PMID 36186864, 2022). "There is only one study that examined the role of IFNG +874T>A polymorphism in schizophrenia." (PMID 24065520, 2013). "Activation of STAT1 is downstream of cytokine receptors that signal from specific pro-inflammatory cytokines known to be dysregulated in schizophrenia, such as IFNγ, IL-6, IL-2, and IL-10." (PMID 40259965, 2025). "The most interesting finding to emerge from all these analyses was indeed that genes involved in synaptic transmission respond differentially to IFNγ and IL-1β exposure in schizophrenia NPCs compared to control NPCs." (PMID 35716830, 2022). "Of these, IFNγ has been found to have increased levels in the plasma of first-episode schizophrenia patients." (PMID 36186864, 2022). "A recent study compared TSPO PET of schizophrenia patients and controls with combined peripheral and CSF measures of IL1β, IFNγ, IL-10, IL-6 and TNF-α." (PMID 32179746, 2020). "In the present study, we report significant association of SNPs in pro-inflammatory cytokine genes IL1A, IL6, TNFA, and IFNG with schizophrenia in the Malayalam-speaking Dravidian population of India." (PMID 27177030, 2016). "The study also provides significant evidence for strong epistatic interactions among pro-inflammatory cytokine genes IL6 and IFNG in the development of schizophrenia." (PMID 27177030, 2016). "Therefore, association of IFNG rs2069718 AA genotype with schizophrenia might be of significance." (PMID 27177030, 2016). "The present study provides evidence of strong independent associations of pro-inflammatory cytokine genes IL1A, IL6, TNFA, and IFNG with schizophrenia and their interactions in Dravidian South Indian population." (PMID 27177030, 2016). "The plasma IL-6 and IFNγ levels were significantly higher in patients with recent onset of schizophrenia compared with controls after excluding these values (P=0.001 and 0.009, respectively)." (PMID 27070405, 2016). "We hypothesised that cortical neural progenitor cells (NPCs) derived from patients with schizophrenia would respond differently to IFNγ or IL-1β exposure compared to those of healthy controls." (PMID 35716830, 2022). "We hypothesise that NPCs derived from patients with schizophrenia will respond differently to IFNγ and IL-1β compared to cells from healthy donors." (PMID 35716830, 2022).
schizophrenia (continued). "Likewise, IL-12, IL-6, TNF and IFNγ peripherical levels are enhanced in patients with schizophrenia, and IL-6 and IL-10 levels elevated in children with ADHD." (PMID 34610039, 2021). "A meta-analysis of 40 studies including 2,572 schizophrenia patients and 4,401 controls revealed consistent elevation of serum interferon gamma (IFN-γ), TNF-α, IL-12, and sIL-2R levels in patients with chronic schizophrenia, independent of disease activity (trait markers)." (PMID 28588507, 2017). "Earlier reports have shown a gender-specific association of IFNG +874A>T (rs2430561) polymorphism with paranoid schizophrenia in males, but not in females." (PMID 27177030, 2016). "These evidences strongly indicate that IFNG rs2069718 may play a role in immune changes occurring in schizophrenia." (PMID 27177030, 2016). "Notably, we were unable to find a significant association between the remaining polymorphisms (IL2 −330T>G, IL6 −174G>C, IFNG +874T>A, TGFB1 +913G>C) and schizophrenia in our study." (PMID 24065520, 2013). "Oxidative stress is hypothesized to contribute to symptomology reported by individuals with schizophrenia, specifically along the Tryptophan/Kynureine/Quinolinic acid pathway, which can be induced by cytokines such as IFNγ, long noted to be abnormally regulated in schizophrenia." (PMID 36386965, 2022). "Because MC5R's association with schizophrenia was identified against the genetic background of a risk allele for the immunomodulatory kynurenine pathway enzyme TDO2, it is most likely that the key action in this case would be the reported inhibition of IFNγ expression by MC5R." (PMID 23847488, 2013). "For example, blood and cerebrospinal fluid concentrations of pro-inflammatory cytokines, including interleukin (IL)-6, IL-8, interferon gamma (IFNγ), tumor necrosis factor alpha (TNF-α), and others, are increased in schizophrenia." (PMID 37239308, 2023). "One meta-analysis showed that acutely relapsed patients with schizophrenia have increased levels of peripheral interleukins (IL) including IL-6, IL-8, tumor necrosis factor alpha (TNF-α), interferon gamma (IFN-γ) but reduced levels of IL-10 when compared with healthy controls." (PMID 33667853, 2021). "Plasma IFNγ was not significantly higher in patients with schizophrenia compared with controls (P=0.03)." (PMID 27070405, 2016). "Cytokine alterations in schizophrenia have been comprehensively investigated in adult schizophrenic patients, with IL-1, 2, 6, 8, 10, and 12 all been observed to increase in schizophrenia, along with TNFα, TGF-β 1, and IFNγ." (PMID 23805069, 2013). "Further clinical studies have found increased biomarkers of neuroinflammation in schizophrenia patients, including greater levels of circulating inflammatory cytokines such as Interleukin-6 (IL-6), Tumour Necrosis Factor Alpha (TNF-α) and Interferon Gamma (IFN-γ)." (PMID 34366935, 2021). "We demonstrate an overall enrichment of both “M1-like” (interferon-alpha, interferon-gamma, lipopolysaccharide acute) and “M2-like” (endotoxin tolerance, glucocorticoid acute) monocyte signatures in the participants with schizophrenia compared to non-psychiatric controls." (PMID 34054608, 2021).